PCSK9 (proprotein convertase subtilisin/kexin type 9)
Diseases named in the same sentence as PCSK9 in open-access papers (continued):
Sharing a sentence is not in itself a finding about the gene and the disease.
Hypercholesterolemia (continued). "The development of PCSK9 inhibitors has become a pivotal strategy in managing hypercholesterolemia and cardiovascular diseases." (PMID 40354375, 2025). "Recent advancements in oral PCSK9 inhibitors have demonstrated promising efficacy in addressing lipid metabolism and hypercholesterolemia in clinical trials or preclinical studies." (PMID 40006605, 2025). "In recent years, inhibitors of PCSK9 have gained significant attention for their role in managing cholesterol levels, especially in patients with hypercholesterolemia." (PMID 39997697, 2025). "We investigated the pharmacodynamics of ZwiLNPs loaded with sihPCSK9 at a lower 1 mg/kg dosage in an HFD-induced PCSK9 humanized transgenic mouse model of hypercholesterolemia." (PMID 40093884, 2025). "PCSK9 inhibitors have been at the centre of hypercholesterolemia research for decades and were discussed in the Drugs and Treatments section (4.3.1)." (PMID 40567825, 2025). "Currently, several clinical trials are underway to evaluate these approaches, particularly those targeting PCSK9 for the treatment of hypercholesterolemia." (PMID 40465697, 2025). "We chose an AAV8-based approach to overexpress the PCSK9 gain-of-function mutant D377Y to induce hypercholesterolemia, allowing us to evaluate the impact of PRDM16 ablation at baseline and during lesion development within the same mouse strains." (PMID 41107595, 2025). "Taken together, our findings demonstrate that the rs6190 SNP promotes hypercholesterolemia and atherosclerosis in vivo through upregulation of Pcsk9 and Bhlhe40 in liver." (PMID 40591411, 2025). "However, the decrease in PCSK9 during effective therapy in UC patients, which may be associated with normalization of cholesterol levels, cannot be explained by the inclusion of patients with hypercholesterolemia." (PMID 40265438, 2025). "PCSK9 inhibitors are safe and effective with statins for hypercholesterolemia post-kidney transplant, and evolocumab reduces cardiovascular events in high-risk patients." (PMID 41478627, 2025). "This highlights the enhanced performance of ZwiLNPs in mediating the silencing of PCSK9, which is crucial for the therapeutic management of hypercholesterolemia." (PMID 40093884, 2025). "RNA-based drugs like inclisiran have shown promise in managing hypercholesterolemia by targeting PCSK9, a gene involved in cholesterol metabolism." (PMID 40110250, 2025). "Statins are the drug of choice for hypercholesterolemia, with ezetimibe, bempedoic acid, and PCSK-9 inhibitors as alternatives in cases of intolerance or as an addition when therapeutic goals are not achieved." (PMID 39941398, 2025). "As we gain a deeper understanding of PCSK9 function, inhibitors targeting it have gradually become important drugs for treating hypercholesterolemia." (PMID 41478627, 2025). "Inclisiran is used to treat hypercholesterolemia or mixed dyslipidemia by inhibiting the hepatic synthesis of proprotein convertase subtilisin–kexin type 9 (PCSK9)." (PMID 39952918, 2025). "induced hypercholesterolemia through PCSK9 gene transfer in APP/PS1 Alzheimer’s mice and observed an increase in plaque burden in the hippocampus by 7 months." (PMID 40405889, 2025).
Hypercholesterolemia (continued). "A similar approach was applied by another group who investigated lipid nanoparticle carrying mRNA encoding adenine base editor, and gRNA targeting PCSK9 in cynomolgus macaques and C57BL/6J mice liver as models of heterozygous familial hypercholesterolemia." (PMID 40725196, 2025). "Currently, available evidence consistently demonstrates and is in good agreement that, in general, the LDL-C-lowering effect of PCSK9 inhibitors is similar across genotypes, except for compound heterozygous and homozygous familial hypercholesterolemia (FH)." (PMID 37610687, 2025). "In pediatric populations with familial hypercholesterolemia, PCSK9 inhibitors show promise, with evolocumab/alirocumab significantly reducing LDL-C and other lipid parameters while being generally well tolerated." (PMID 40764605, 2025). "Another important risk modifier is familial hypercholesterolemia, which is caused by functional mutations in the LDL receptor, apolipoprotein B, or Proprotein Convertase Subtilisin/Kexin type 9 (PCSK9) genes." (PMID 40217673, 2025). "We identified a variant in PCSK9 (UniProt ID: Q8NBP7), p.Ser47Cys (NM_174936.4: c.140C>G), reported in patients with familial hypercholesterolemia (OMIM #603776)." (PMID 41301500, 2025). "The intense interest and efforts in search of small-molecule orally active inhibitors of PCSK9 reflect a vital shift in addressing the condition of hypercholesterolemia." (PMID 40305153, 2025). "One such therapy, inclisiran, a GalNAc-conjugated siRNA targeting PCSK9, has been approved for treating adults with heterozygous familial hypercholesterolemia or clinical atherosclerotic CVD." (PMID 40076813, 2025). "Additional evidence from trials such as ODYSSEY DM-INSULIN and ODYSSEY DM-DYSLIPIDEMIA highlighted the efficacy of PCSK9 inhibitors in individuals with hypercholesterolemia and diabetes." (PMID 40076813, 2025). "Camilla Gustafsen identified sortilin, encoded by the hypercholesterolemia risk gene SORT1, as a high-affinity sorting receptor for PCSK9." (PMID 39858645, 2025). "PCSK9 represents the third gene involved in familial hypercholesterolemia, after LDL-R and ApoB genes." (PMID 40305153, 2025). "Among the most advanced candidates is Verve Therapeutics’ VERVE-101, a CRISPR-based therapy targeting the PCSK9 gene, now in Phase 1 clinical trial for familial hypercholesterolemia." (PMID 40465697, 2025). "Another target is PCSK9 for the treatment of familial hypercholesterolemia, with adenine base editors delivered as mRNA LNPs." (PMID 40880534, 2025).
Hypercholesterolemia (continued). "The modern treatment for hypercholesterolemia encompasses the use of biological drugs against PCSK9, like monoclonal antibodies and gene expression modulators such as inclisiran—a short, interfering RNA (siRNA)." (PMID 38338741, 2024). "As a consequence, PCSK9 has been identified as a crucial target for drug development against dyslipidemia and hypercholesterolemia, aiming to lower plasma LDL-C levels." (PMID 38397888, 2024). "Cholesterol-lowering with PCSK9 inhibitors attenuates the pro-inflammatory profile of monocytes in patients with hypercholesterolemia." (PMID 39149582, 2024). "Targeting PCSK9 is not only effective for the treatment of hypercholesterolemia but also promising for cancer therapy." (PMID 39324018, 2024). "Because of its significant medical importance, numerous solutions have been investigated to achieve a reduction in the PCSK9 molecule number or activity in order to lower the hypercholesterolemia level." (PMID 38338741, 2024). "In resistant hypercholesterolemia, proprotein convertase subtilisin/kexin type 9 (PCSK9) inhibitors (evolocumab and alirocumab) are effective and safe choice, hence they do not alter glucose homeostasis and they do not trigger new onset of diabetes." (PMID 39140033, 2024). "This significant reduction can contribute to a decreased probability of CV events in patients with hypercholesterolemia, making PCSK9 inhibitors an essential option for high cholesterol management." (PMID 39539858, 2024). "GOF mutations result in the enhancement of the ability of PCSK9 to upregulate LDL-C, leading to hypercholesterolemia." (PMID 39736777, 2024). "PCSK9 is not only a promising therapeutic target for hypercholesterolemia, but also applied in the development of experimental animal models for atherosclerosis." (PMID 39149582, 2024). "PCSK9 inhibitors were proven highly effective for hypercholesterolemia and atherosclerotic cardiovascular disease in a previous meta-analysis." (PMID 39975967, 2024). "Our findings highlight the potential of ferritin‐based platforms as versatile tools for targeting PCSK9 in the management of hypercholesterolemia." (PMID 39150051, 2024). "We propose that miR-99a-5p can potentially serve as an inhibitor of PCSK9 to promote LDL-C uptake in hepatocytes to ameliorate hypercholesterolemia and atherosclerosis." (PMID 39628814, 2024). "Proprotein convertase subtilisin/kexin type 9 (PCSK9) has evolved as a pivotal enzyme in lipid metabolism and a revolutionary therapeutic target for hypercholesterolemia and its related cardiovascular diseases (CVD)." (PMID 38185721, 2024). "Gain-of-function variants in PCSK9 lead to increased plasma LDL-C concentrations and hypercholesterolemia, while loss-of-function variants are associated with reduced plasma LDL-C and decreased CHD risk." (PMID 38796450, 2024). "PCSK9 inhibitors (evolocumab, alirocumab) for hypercholesterolemia, neprilysin inhibitors for heart failure, IL-5 inhibitors for asthma." (PMID 39539858, 2024). "Toward that end, Vaxxinity has developed VXX-401, a novel anti-PCSK9 vaccine for the treatment of hypercholesterolemia and long-term prevention of ASCVD." (PMID 38216056, 2024). "Treatment of hypercholesterolemia with statins counteracts the disease in part through upregulation of PCSK9." (PMID 39057707, 2024). "PCSK9 increases the degradation of the LDL-receptor and reduces LDL-C clearance, causing hypercholesterolemia." (PMID 39094771, 2024). "This highlights a cardioprotective function of PCSK9 suppression in HFD, which conforms with the use of PCSK9 inhibitors such as alirocumab (Praluent) and evolocumab (Repatha) for treatment of patients with hypercholesterolaemia." (PMID 39420340, 2024).
Hypercholesterolemia (continued). "Taken together, HFD-induced hypertriglyceridemia promotes renal FFA retention and ferroptosis, whereas PCSK9-GOF–induced hypercholesterolemia elicits ER stress, both resulting in renal fibrosis." (PMID 39094771, 2024). "As the understanding of PCSK9 role in the pathogenesis of hypercholesterolemia evolved, efforts devoted to this unique pathway led to the development of monoclonal antibodies against PCSK9." (PMID 38672532, 2024). "Proprotein convertase subtilisin/kexin type 9 (PCSK9) plays a crucial role in cholesterol metabolism by regulating LDL receptor degradation, making it a therapeutic target for mitigating hypercholesterolemia‐associated risks." (PMID 39150051, 2024). "This innovative approach holds promise for individuals with hypercholesterolemia and contributes to the expanding armamentarium of PCSK9-targeted therapies." (PMID 38105401, 2024). "Inclisiran, a novel drug approved for hypercholesterolemia treatment, acts by inhibiting PCSK9 protein translation in hepatocytes." (PMID 38398034, 2024). "In this study, we have unraveled the pleiotropic effects of statins on hypercholesterolemia via epigenetic regulation of PCSK9." (PMID 39566851, 2024). "The advent of PCSK9 inhibitors marks a significant advancement in pharmacological lipid-lowering therapy, particularly for the treatment of primary hypercholesterolemia and the prevention of cardiovascular events." (PMID 38828451, 2024). "Taken together, these findings provide a compelling testament to the potential of VXX-401 as a PCSK9 inhibitor for the treatment of hypercholesterolemia." (PMID 38216056, 2024). "Familial hypercholesterolemia is caused primarily by mutations in the gene encoding the LDL receptor (LDL-R), with less frequent mutations in the apolipoprotein B (APOB) and proprotein convertase subtilisin/kexin type 9 (PCSK9) genes." (PMID 39350832, 2024). "Clinically, PCSK9 inhibitors, often used in conjunction with statins, have been frequently applied to reduce cardiovascular adverse events in the treatment of hypercholesterolemia." (PMID 39722825, 2024). "Research by Roberto suggests that PCSK9 inhibitors significantly improve lipid levels in male patients with familial hypercholesterolemia, thereby enhancing erectile function." (PMID 38741592, 2024). "Background and Objectives: The proprotein convertase subtilisin-kexin type 9 (PCSK9) inhibitors evolocumab and alirocumab are recently developed promising drugs used for treatment of familial hypercholesterolemia (FH)." (PMID 39459433, 2024). "Murine proprotein convertase subtilisin/kexin type 9 (Pcsk9) was chosen as target gene for in vivo verification, due to its potential in treating familial hypercholesterolemia." (PMID 38671524, 2024). "Wasserman's focused on evolocumab (AMG145) for lipid-lowering, a PCSK9 inhibitor, as well as its efficacy and safety for cardiovascular events and PCSK9 in familial hypercholesterolemia." (PMID 38887452, 2024). "The third study, sponsored by Verve Therapeutics, was the first to evaluate a base editing platform using an ABE to disrupt the expression of the PCSK9 gene, to treat heterozygous familial hypercholesterolemia." (PMID 39246827, 2024). "Inclisiran requires less frequency than monoclonal antibody regimen administration and has similar safety and efficiency in reducing LDL-C and PCSK9 levels, as shown in studies for both primary and secondary prevention and familial hypercholesterolemia." (PMID 39274253, 2024). "A new PCSK9 inhibitor tested in patients with familial and non-familial hypercholesterolemia is Tafolecimab, a fully human monoclonal antibody directed against PCSK9." (PMID 39685877, 2024).
Hypercholesterolemia (continued). "Since the identification of the causative gene, proprotein convertase subtilisin-kexin type 9 (PCSK9), in familial hypercholesterolemia family lines in 2003, the development of PCSK9-targeted inhibitors has progressed rapidly." (PMID 38390206, 2024). "PCSK9 inhibitors are now widely used as a new class of lipid-lowering drugs in a wide range of patients with cardiovascular diseases, including familial hypercholesterolemia." (PMID 38390206, 2024). "Two PCSK9 inhibitors currently on the market, evolocumab and alirocumab, have been used to treat patients with familial hypercholesterolemia." (PMID 38940622, 2024). "Proprotein convertase subtilisin/kexin type 9 (PCSK9) was first reported in 2003 and confirmed to be strongly associated with familial hypercholesterolemia." (PMID 39736777, 2024). "Typically administered as adjunctive therapy, PCSK9 inhibitors are particularly useful in individuals with familial hypercholesterolemia or those requiring additional LDL-C lowering despite maximum statin therapy." (PMID 38961447, 2024). "The PCSK9 antibodies evolocumab and alirocumab target the PCSK9 enzyme in plasma and were the first biologics approved for heterozygous familial hypercholesterolemia (HeFH), as well as for resistant hyperlipidemias." (PMID 38668084, 2024). "Proprotein convertase subtilisin/kexin type 9 (PCSK9) is a protein primarily known to regulate plasma low-density lipoproteins (LDLs) rich in cholesterol and to be one of the main causes of familial hypercholesterolemia." (PMID 39769398, 2024). "PCSK9 inhibitors significantly lower LDL‐C and reduce cardiovascular events, offering promising therapies for high‐risk patients, including those with familial hypercholesterolemia (FH) and those who cannot tolerate statins." (PMID 39479289, 2024). "In the ODYSSEY open-label extension study, spanning an average observation period of 2.5 years, no significant increase in sudden adverse events was observed in patients with familial hypercholesterolemia undergoing PCSK9 monoclonal antibody treatment." (PMID 39139638, 2024). "In 2015, the FDA approved two PCSK9 inhibitors, Alirocumab and Evolocumab, for adults with familial hypercholesterolemia (HeFH) or atherosclerotic cardiovascular disease (ASCVD) who need further LDL-C reduction." (PMID 39770423, 2024). "However, despite these constraints, the study provides preliminary results that may support the increasing recognition of PCSK9 inhibitors and inclisiran as a novel and efficacious treatment option for patients with familial hypercholesterolemia or those at very high risk of cardiovascular diseases." (PMID 39064553, 2024). "A total of 5,600 keywords, the most frequently occurring keywords were PCSK9 (903 times), cardiovascular disease (804 times), statin therapy (790 times), familial hypercholesterolemia (787 times), PCSK9 inhibitor (539 times), and cholesterol (509 times)." (PMID 38887452, 2024). "The monoclonal antibodies evolocumab and alirocumab are prominent examples of PCSK9 inhibitors, demonstrating robust efficacy in reducing cardiovascular events in patients with hypercholesterolemia and those intolerant to statins." (PMID 39131016, 2024). "Specifically, miR-191, miR-222, and miR-224 miR-483-5p control PCSK9 expression, enhanced hypercholesterolemia, and LDL-C uptake in mice liver fed with a high-fat diet." (PMID 36980601, 2023). "Our atherosclerosis model was based on intravenous delivery of the AAV8 vector encoding Pcsk9, a protein controlling the expression of LDL receptor in the liver what, in combination with high-fat feeding, induces hypercholesterolemia in mice." (PMID 37965327, 2023).